CLCA4 (chloride channel accessory 4)
Diseases named in the same sentence as CLCA4 in open-access papers (continued):
Sharing a sentence is not in itself a finding about the gene and the disease.
esophageal cancer (1 paper, 2021). A primary or metastatic malignant neoplasm involving the esophagus. "In this study, through bioinformatics analysis, it was found that the expression of CLCA4 was low in esophageal cancer tissues." (PMID 34194494, 2021). "Moreover, the low expression of CLCA4 promoted the cell progression of esophageal cancer cells in vivo and in vitro." (PMID 34194494, 2021).
head and neck squamous cell carcinoma (1 paper, 2021). A squamous cell carcinoma that arises from any of the following anatomic sites: lip and oral cavity, nasal cavity, paranasal sinuses, pharynx, larynx, and salivary glands. "CLCA4 overexpression was found to significantly decline the cell proliferation and metastasis ability in head and neck squamous cell carcinoma cells." (PMID 34194494, 2021).
liver cirrhosis (1 paper, 2018). "Kaplan-Meier analysis revealed that the patients with low CLCA4 expression (P < 0.001), high AFP level (P < 0.001), high GGT level (P = 0.017), liver cirrhosis (P = 0.007), larger tumor (P < 0.001) and vascular invasion (P < 0.001) had shorter OS time." (PMID 30312171, 2018). "In addition, low CLCA4 expression (P < 0.001), high AFP level (P = 0.004), high GGT level (P = 0.010), liver cirrhosis (P = 0.019), larger tumor (P < 0.001), satellite nodule (P = 0.002) and vascular invasion (P < 0.001) were unfavourable prognostic factors for TTR of HCC patients." (PMID 30312171, 2018). "On the contrary, CLCA4 expression had no significance with gender, age, AFP level, HBsAg, gamma-glutamyltransferase (GGT), liver cirrhosis, tumor number, satellite nodule, tumor differentiation and BCLC stage (all P > 0.05)." (PMID 30312171, 2018).
oral cancer (1 paper, 2020). "Bundela also found multiple differentially expressed genes in oral cancer patients in India, and suggested that CLCA4 may be a potential therapeutic target." (PMID 32797167, 2020).
Osteochondrosis (1 paper, 2020). Abnormal growth ossification centers in children. "Although another member of CLCA family, CLCA4, has been reported to be associated with osteochondrosis in the horse, CLCA2 has not been associated with bone formation or any musculoskeletal disorders." (PMID 32131869, 2020).
tumor (24 papers, 2009 to 2025). "The correlation analysis of CLCA4 expression revealed a significant association between CLCA4 expression and tumor size (P = 0.001) and tumor stage (T classification) (P = 0.034)." (PMID 29190973, 2017). "CLCA4 is a tumor suppressor and a member of the calcium-activated chloride channel protein family, which is associated with the growth, proliferation, migration, and invasion of tumor cells." (PMID 36532007, 2022). "Our results suggest that CLCA4 status is associated with tumor progression and could be used as prognostic factor for HCC patients." (PMID 30312171, 2018). "The frequent loss of CLCA4 expression with tumor progression suggested that CLCA4, like CLCA2, might antagonize tumorigenesis." (PMID 24386311, 2013). "This is in line with several previous studies on CRC in which human CLCA4 had been had been found down-regulated in tumor tissues." (PMID 40220130, 2025). "Under tumorous conditions, no or only marginal expressions of Clca4a and -4b were detected in tumor cells of a murine model of CRC as well as CLCA4 in the human CRC." (PMID 40220130, 2025). "The expression of TF-protein YY1 (a regulator of CXCL8, ADH1C, CEMIP, ZG16, and CLCA4) contributes to tumor growth differs in different cancers." (PMID 36991484, 2023). "Chloride channel accessory 4 (CLCA4) is well known as a tumor inhibitor and has been shown to suppress the development of various malignant tumors." (PMID 35300114, 2022). "CLCA4 was found to act as a tumor suppressor gene in some cancers, but its role in ESCA is still unclear." (PMID 34194494, 2021). "Animal experiments were conducted to investigate the role of CLCA4 upregulation in tumor growth in vivo." (PMID 34194494, 2021). "In this study, the role of CLCA4 as a tumour inhibitor in the occurrence and development of HNSCC was verified." (PMID 34663338, 2021). "Many tumour suppressors, such as Calcium activated chloride channel A4 (CLCA4), have been widely accepted as a marker related to tumour progression, including BCa." (PMID 33830879, 2021). "After knockout of CLCA4, it is found that tumors induce tumor cell differentiation and metastasis through epithelial-mesenchymal transition." (PMID 32462020, 2020). "CLCA4 is also known as a tumor suppressor, which can promote the development of many types of malignant tumors." (PMID 32462020, 2020). "The biological function of CLCA4 in inhibiting tumor invasion was further supported in vivo experimental metastasis assay." (PMID 30312171, 2018). "As Epithelial-mesenchymal transition (EMT) is one main process of tumor cell migration and invasion, we therefore evaluated the effect of CLCA4 on the expression of EMT-related markers." (PMID 30312171, 2018). "We further examined the in vivo effects of CLCA4 on tumor invasion in Hep-3B and SMMC-7721 xenografts in vivo." (PMID 30312171, 2018). "The expression of CLCA4 was negatively correlated with tumor size (P = 0.030), vascular invasion (P = 0.004) and TNM stage (P = 0.044)." (PMID 30312171, 2018). "As EMT is one main process of tumor cell migration and invasion, western blot assay was performed to evaluate the effect of CLCA4 on the expression of EMT-related factors." (PMID 29190973, 2017). "Both are precipitously downregulated with tumor progression (it should be noted that CLCA4 was misidentified as CLCA2 in that study)." (PMID 24386311, 2013). "Both CLCA1 and CLCA4 are expressed in the intestine, may act as tumor suppressors, and are negatively correlated with tumor formation." (PMID 35693937, 2022). "In addition, the tumor xenograft experiment was performed to detect the function of CLCA4 on the tumorigenicity in vivo." (PMID 34194494, 2021). "CLCA4 was suggested to act as a tumor inhibitor in ESCA and might be a therapeutic target gene for the treatment of patients with ESCA." (PMID 34194494, 2021). "Further analysis revealed that CLCA4 is a marker of breast epithelial differentiation and may be involved in tumor proliferation and metastasis." (PMID 32797167, 2020).
tumor (continued). "In addition, CLCA4 expression was negatively correlated with tumor size, vascular invasion and TNM stage." (PMID 30312171, 2018). "CLCA4 expression was negatively correlated with tumor size, vascular invasion and TNM stage." (PMID 30312171, 2018). "There were more numbers of tumor nodules on the lungs surface of mice when CLCA4 was silenced." (PMID 30312171, 2018). "Like the results of IHC and western blotting, the RT-PCR results found that decreased expression of E-cadherin and increased expression of vimentin and N-cadherin in CLCA4-silenced cells compared with the control tumor cells, while opposite expression was observed in CLCA4-transfected cells." (PMID 30312171, 2018). "In vivo experiments confirmed the tumor suppressor role of CLCA4." (PMID 29190973, 2017). "In addition, some reports have revealed involvement of CLCA1, CLCA2, and CLCA4 in tumor progression." (PMID 29190973, 2017). "Moreover, we showed that CLCA4 expression were significantly correlated with tumor stage and tumor size." (PMID 29190973, 2017). "Moreover, CLCA4 overexpression suppressed tumor growth in vivo." (PMID 34194494, 2021). "Experimental downregulation of CLCA4 seemed to promote epithelial-to-mesenchymal transition (EMT) of neoplastic cells, facilitating tumor growth, invasion, and metastasis." (PMID 40220130, 2025). "SPINK1, FABP4, and MMP10 showed darker staining in tumor tissues, and GPRASP1, CLCA4, and LAMP5 showed lighter staining." (PMID 35479956, 2022). "According to the HPA database, the protein levels of SLC26A3, GUCA2A, CLCA4, CLCA1, and AQP8 in tumor tissues were all significantly lower than that in normal tissues." (PMID 35693937, 2022). "Therefore, our findings confirmed that CLCA4 might block tumor growth and motility in ESCA." (PMID 34194494, 2021). "Five of the proteins (involucrin, CLCA4, S100A14, Serpin B5 and myosin-11) were found in the Pap test fluid; four of these proteins were also found in either the swab or tumor samples." (PMID 33413078, 2021). "It is a novel self-cleaving extracellular metalloprotease and is a homologue of likely tumor suppressors, CLCA2 and CLCA4." (PMID 29515771, 2018). "Our findings suggest that CLCA4 could impede colorectal CSC self-renewal by interacting with vimentin to suppress the FAK signaling pathway, potentially reducing tumor cell stemness and evading immune surveillance." (PMID 41674659, 2025). "Database analysis revealed that the mRNA level of chloride channel accessory 4 (CLCA4) was frequently lower in primary tumor tissues than in non-cancerous colon tissues and even lower in liver metastases." (PMID 39035991, 2024). "Patients with low CLCA4 expression predicted poor OS and TTR times in all of these subgroups for except OS and TTR in patients who had vascular invasion (P = 0.410, and P = 0.131) or OS in patients with tumor size ≤ 5 cm (P = 0.081)." (PMID 30312171, 2018).
cancer (20 papers, 2013 to 2025). A tumor composed of atypical neoplastic, often pleomorphic cells that invade other tissues. "Reduced chloride channel accessory 4 (CLCA4) levels are linked to cancer development, while its role and mechanism in cancer stem cells (CSCs) remain unclear." (PMID 41674659, 2025). "In CRC and many other cancers, CLCA4 mutation has a decreased prevalence (0.44% of CRC)." (PMID 34638601, 2021). "Cancer-associated fibroblasts exosomes decreased the sensitivity of CRC towards the radiation and over-expressed miR-590-3p that promote CLCA4-dependent PI3K/Akt signaling pathway as well as cancer cell survival." (PMID 36991484, 2023). "It has been well established that CLCA4 plays an important role in carcinomatosis in several cancer types." (PMID 30312171, 2018). "Conversely, increased N-cadherin, vimentin, fibronectin, Zeb1, Twist, and Snail expression and down-regulation of E-cadherin were detected in CLCA4 silenced cancer cells." (PMID 29190973, 2017). "Besides CLCA1, it has also been showed that CLCA4 contributes to the progression of several types of malignant tumors including CRC." (PMID 35907803, 2022). "Recent studies have shown that the expression levels of CLCA proteins, including CLCA1 and CLCA4, are abnormal in many cancer types so it may be a potential cancer predictor for patients." (PMID 35693937, 2022). "CLCA4 expression is downregulated in human cancers including CRC." (PMID 34638601, 2021). "Interestingly, down-regulation of E-cadherin and increased vimentin and N-cadherin expression were observed in CLCA4 silenced cancer cells." (PMID 30312171, 2018). "CLCA1, CLCA2, and CLCA4 have all been implicated in various cancers as have a number of TMEM16 proteins, and such studies could have tremendous implications for cooperative CLCA/TMEM16 roles in cancer and other diseases." (PMID 25781344, 2015). "Therefore, CLCA4 and MS4A12 might be cancer suppressors which could be beneficial to the progression of patients with PCRC." (PMID 32797167, 2020). "In addition, more and more evidence found that the expression of CLCA proteins was abnormal in a variety of cancers, such as CLCA1, CLCA2 and CLCA4, which could be potential predictors for patients." (PMID 30312171, 2018).
CLCA4 also shares sentences with these, for which no sentence is quoted: gastric cancer (3 papers); breast tumors (2); head and neck cancer (2); adenocarcinoma (1); adenoma (1); Chronic colitis (1); Crohn disease (1); kidney stone (1); liver cancer (1); musculoskeletal disorders (1); ovarian carcinoma (1); pancreatic cancer (1); pancreatic ductal adenocarcinoma (1); polyp (1); stomach cancer (1).